CD68 (CD68 molecule)
Diseases named in the same sentence as CD68 in open-access papers (continued):
Sharing a sentence is not in itself a finding about the gene and the disease.
myocardial infarction (21 papers, 2010 to 2025). Gross necrosis of the myocardium, as a result of interruption of the blood supply to the area, as in coronary thrombosis. "Recent studies have shown that there is increased expression of ADAMTS-1 in plaques from patients with acute myocardial infarction which is associated with increased CD68 staining." (PMID 24732590, 2014). "A recent demonstrated that there is increased expression of ADAMTS-1 which is associated with CD68 staining in patients with acute myocardial infarction." (PMID 24732590, 2014). "Administration of BMSC-exosomes can enhance cardiac repair in myocardial infarction (MI) patients by downregulating CD68 expression." (PMID 39682706, 2024). "CD68 staining showed very few signals in CLP heart sections while strongly stained the macrophage in the infarcted heart after myocardial infarction (positive control for CD68 staining)." (PMID 39726718, 2024). "For example, immunohistostaining of mice one-week post-myocardial infarction indicated colocalization of TSPO to CD68+ microglia and cardiac monocytes within the brain cortex and infarcted myocardium respectively." (PMID 37108685, 2023). "CD68 has previously been shown to be increased in infarcted and remote tissue post-myocardial infarction." (PMID 37823919, 2023). "One week after myocardial infarction induction, hearts sections were stained with anti-CD68 antibody to identify infiltrated inflammatory cells in infarcted myocardium." (PMID 28203568, 2017). "Recruitment of inflammatory cells to the border zone of the infarction was evaluated 3 days after myocardial infarction by staining for mononuclear CD68+ cells." (PMID 20849606, 2010). "Interestingly, the continued administration of Uro B for 14 days remarkably improved CD68+ macrophage infiltration, which was further validated by a decrease in CD68 mRNA expression in rats after myocardial infarction." (PMID 35814202, 2022). "However, there was an increase of all CD68+ macrophages in MI hearts in comparison to healthy hearts, indicating an influx of newly recruited monocytes/macrophages as expected upon myocardial infarction." (PMID 37063955, 2023). "Macrophage infiltration is part of the local inflammatory response following myocardial infarction and here we examined this process in VEH or STZ mice subjected to IR by staining for the macrophage marker CD68." (PMID 22347376, 2012). "The existence of FFAR2+ and FFAR3+ cells in human myocardial infarction tissue, by immunofluorescent co-staining for FFAR2/3 and canonical marker genes of monocytes and macrophages (CD14, CX3CR1, and CD68), indicating the existence of FFAR2/3 positive monocytes and macrophages." (PMID 40308581, 2025). "Myocardial infarction led to the abundant expression of inflammatory factory CD45 and CD68." (PMID 31892842, 2020).
Arthritis (19 papers, 2015 to 2025). Inflammation of a joint. "In the context of hyperalgesia, an enhanced activation and infiltration of CD-68-positive macrophages has been observed in animal models of arthritis-associated pain, peripheral nerve injury, and paclitaxel chemotherapy-induced peripheral neuropathy." (PMID 36361909, 2022). "This could be associated with arthritis, as evident from increased CD68+ macrophage infiltration." (PMID 27792788, 2016). "Cilostazol has also been shown to significantly attenuate the expression of IL-23 co-localized with CD68+ macrophages in the knee synovium of CIA mice through cAMP-dependent protein kinase activation while reducing the severity of arthritis." (PMID 35958604, 2022). "Methyl palmitate has been shown to inhibit the expression of CD68+ SMs in adjuvant-induced rat models of arthritis and can exert potential anti-inflammatory effects." (PMID 35958604, 2022). "In fact, the synovial membrane of arthritis animals presented a significant number of macrophages CD68+, lymphocytes CD20+ and lymphocytes CD3+T compared to other groups." (PMID 30059520, 2018). "Circulating monocytes also transmigrate across the blood-nerve barrier in sensory ganglia and take on a macrophage-like phenotype, in a preclinical inflammatory pain model, and CD68+ macrophages migrate into DRG in antigen-induced arthritis progression." (PMID 29548992, 2018). "In the mBSA arthritis model, 30 days after the induction the inflammatory infiltrate in the synovial membrane, the region was rich in CD68+ macrophages, CD3+ lymphocytes and CD20+ lymphocytes, culminating with fibroblast proliferation after 45 days." (PMID 30059520, 2018). "Patients PT3 and PT8 of Group-1 showed more CD68+ macrophages, indicating the severity of chronic inflammation due to arthritis compared to the other two patients (PT6 and PT10) with arthritis." (PMID 27792788, 2016). "The presence of CD68+ macrophages in Group-1 specimen implied an inflammatory phase imparted due to arthritis." (PMID 27792788, 2016). "This increased expression can be attributed to the increased cell number contributed by infiltrated CD68+ macrophage as a result of inflammation and arthritis." (PMID 27792788, 2016). "Several experimental compounds have also shown an association between control of arthritis and reduction in the number of CD68 macrophages in animal models of arthritis." (PMID 26658436, 2015). "Of interest, in the preclinical test of new compounds, a number of observations have shown that effective RA treatments such as tofacitinib and methotrexate also decrease CD68 sublining macrophages in animal models of arthritis." (PMID 26658436, 2015). "It remains to be elucidated if IL26-positive CD68+ synovial macrophages stem from circulating monocytes or from synovial tissue-resident macrophages, which both have been demonstrated in the K/BxN serum-transfer arthritis model." (PMID 38799447, 2024). "Furthermore, CP-25 alleviated kidney injuries in rats with arthritis through reducing the number of renal CD68+ cells and downregulating the levels of TNF-α and IL-6." (PMID 36457713, 2022). "CD68+ SMs act as pro-inflammatory macrophages that accelerate the onset of arthritis." (PMID 35958604, 2022). "Notably, AIA rats with advanced arthritis showed an excessive abundance of CD68+ macrophages and synovial hyperplasia, consistent with the results of hematoxylin and eosin (H&E) assay." (PMID 33846342, 2021). "Based on H&E and immunohistochemistry staining for CD3 (T cells), CD20 (B cells), CD138 (plasma cells), and CD68 (macrophages), synovial tissue from each UA and definite arthritis group was categorized into three distinct synovial pathotypes: lympho-myeloid, diffuse-myeloid, and pauci-immune." (PMID 33679701, 2020).
Arthritis (continued). "Our aim in the herein study was to test the effect of celastrol treatment in the number of sublining CD68 macrophages and on the overall synovial tissue cellularity and joint structure in an animal model of arthritis, as a further argument to its possible efficacy in RA treatment." (PMID 26658436, 2015). "Moreover, we found that seronegative UPIA patients who differentiate into further defined arthritis, show higher expression of lining and sublining CD68+ cells, sublining CD3+ cells, increased number of CD31+ vessels and higher IL-6 PB levels than patients who remain as UPIA during the follow-up." (PMID 30018954, 2018). "Our main goal in this work was to test the effect of celastrol in the number of sublining CD68 macrophages (a biomarker of therapeutic response for novel RA treatments) and on the overall synovial tissue cellularity and joint structure in the adjuvant-induced rat model of arthritis (AIA)." (PMID 26658436, 2015). "MANF mRNA is highly increased in peripheral white blood cells of RA patients as well as in the synovium of rabbit arthritis model, for which MANF was mainly localized in the cytoplasm of a-SMA-positive FLS and poorly in CD68-positive macrophage-like synoviocytes." (PMID 35008858, 2021).
sarcoma (19 papers, 2018 to 2025). A usually aggressive malignant neoplasm of the soft tissue or bone. "In a recent study of almost 200 STSs, infiltration of CD68+ macrophages was shown to be an independent biomarker of a higher risk of local recurrence in sarcomas." (PMID 37296922, 2023). "These sarcomas had a significantly higher CD68: TIL ratio than translocation-associated sarcomas, which was confirmed by immunohistochemistry and the analysis of mRNA expression." (PMID 37958467, 2023). "Seventy-five sarcoma specimens (not limited to a single histological type), resected at our institution, were collected, and the number of CD68-, CD163-, and CD204-positive macrophages in the intratumoral and marginal areas was counted." (PMID 36690825, 2023). "In cases of high-grade sarcoma, especially undifferentiated sarcoma, the sarcoma cells themselves are sometimes CD68-positive." (PMID 36690825, 2023). "Another marker, CD68, was particularly prominent among translocation-free sarcomas, especially pleomorphic liposarcoma, chordoma, chondrosarcoma (conventional and dedifferentiated subtypes), UPS, and angiosarcoma." (PMID 37958467, 2023). "Apart from the sparse presence of TILs (0–8%), macrophages (CD68-positive cells) were observed in 71% of cases, which was in line with a recent study showing that CD68-positive macrophages outnumbered TILs in various sarcomas." (PMID 35628499, 2022). "Synovial sarcomas had lower CD68 staining than other sarcomas." (PMID 30999901, 2019). "Post– minus pre-treatment CD68 staining scores were lower in synovial sarcomas than other sarcomas." (PMID 30999901, 2019). "Immunohistochemical positivity for CD68 (a histiocytic marker also highly expressed in cells of monocyte lineage and circulating and tissue macrophages) is frequently reported in undifferentiated sarcomas, and this was observed in the present case." (PMID 31773099, 2019). "The association between CD68+CD163+ macrophages and metastasis-free survival highlights the complexity of macrophage biology, given that CD163+ macrophages have traditionally been associated with worse outcomes in many solid tumors, including various sarcoma subtypes." (PMID 40601026, 2025). "We investigated the numbers of CD68-, CD163-, and CD204-positive macrophages in the intratumoral and marginal areas of sarcoma cases." (PMID 36690825, 2023). "Other markers, characteristic of sarcoma TAMs, are CD163 and CD68, specific for M2 and M1 macrophages, respectively." (PMID 37958467, 2023). "Although there was similar density of CD68 (staining pan-macrophages) and CD163 (staining M2-polarized macrophages) in fibroblastic sarcoma, only high density of CD163 indicated higher tumor staging." (PMID 34257571, 2021). "Relationship between CD68, CD163 and CD33 density and patient characteristics of fibroblastic sarcomas." (PMID 34257571, 2021). "UPS is known to have increased infiltration of CD68+ macrophages and CD163+ TAMs among the various subtypes of sarcoma." (PMID 33802565, 2021). "Abundant accumulation of CD68 and CD163-positive macrophages in sarcoma is also elucidated in a study involving 24 types of sarcoma including DFSP and MFS." (PMID 34257571, 2021). "The sarcomas contained CD16-negative histiocytes (20% ± 17%) and phagocytes (CD68+ CD163−; 5% ± 10%), these latter in 7/21 cases." (PMID 31959856, 2020). "Synovial sarcomas exhibited lower CD68 and CD44 staining, and less macrophage infiltration than the other sarcomas in our study." (PMID 30999901, 2019). "Histiocytic sarcoma cells are derived from bone marrow monocyte precursors, expresses monocyte-macrophage antigens (CD163, CD68, and lysozyme) and lack expression of myeloid antigens such as CD33, CD13 and MPO." (PMID 29463311, 2018). "Undifferentiated sarcoma (UC) might be a possibility based on the cells’ immunstaining features (SMA+ and CD68+)." (PMID 37007164, 2023).
sarcoma (continued). "Remarkably, even broadly mesenchymal markers vimentin and CD68 were negative, a finding typically seen in undifferentiated pleomorphic sarcomas." (PMID 35501497, 2023). "Correlation analysis revealed that the density of CD68, CD163 and CD33 was not only positively correlated with the total score of HMGB1, but also with the cytoplasm-staining score of HMGB1 in fibroblastic sarcomas." (PMID 34257571, 2021). "In fibroblastic sarcomas, the total score and the cytoplasm-staining score of HMGB1 were positively correlated with CD68, CD163 and CD33 density, indicating that HMGB1 may act on M2-polarized TAMs and CD33-positive myeloid cells in fibroblastic sarcomas and contribute to disease progression." (PMID 34257571, 2021). "Furthermore, the expression of CD47 and SIRPA showed poor positive correlations with CD68+ and CD163+ macrophages in almost all sarcomas, except a solitary fibrous tumor, demonstrating a significant negative correlation between CD163+ and CD68+ TAMs, and CD47." (PMID 37958467, 2023).
adenoma (18 papers, 2010 to 2025). A neoplasm arising from the epithelium. "Our study provides evidence that CD68+ cell expression rises along the stages of the adenoma–carcinoma transition." (PMID 40149674, 2025). "Thyroid carcinomas demonstrate high immunogenicity compared to adenomas with extensive infiltration by CD8+, CD68+ and CD163+ macrophages, associated with increased expression of SMAD4 and STAT6 in tumor cells." (PMID 39936166, 2025). "Future studies are advocated to fully characterize CD68+ macrophages, to differentiate M1‐polarized and M2‐polarized macrophages, and to investigate adenoma cytokines in patients naïve to SRL or pretreated with SRLs at the surgery." (PMID 40789673, 2025). "GH adenomas show higher infiltration of B cells and CD8+ T cells, Gn adenomas exhibit increased infiltration of CD68+ macrophages, while ACTH adenomas display elevated infiltration of CD8+ T cells." (PMID 38716256, 2024). "The values of Ripley’s H indicate spatial attraction between MUC5AC+ and CD68+ cells in SSLs, but spatial repulsion between these two in adenomas." (PMID 38833684, 2024). "They found that null cell adenomas and sparsely granulated GH-secreting adenomas had higher CD68+ cell infiltration than the other two subtypes." (PMID 34925244, 2021). "Quartz particles were observed in the fibrotic area, in the granuloma, in macrophages in the alveolar space (positive for CD68), and in neoplastic lesions (adenoma of the lung)." (PMID 32313071, 2020). "CD68 expression was higher in sparsely granulated GH adenomas and null cell adenomas than in densely granulated GH-secreting adenomas and adrenocorticotropic hormone (ACTH)-secreting adenomas." (PMID 33362722, 2020). "Immunostaining with CD68 showed a remarkable increase in the presence of CD68-positive cells in AIPpos tumors compared to sporadic adenomas (P = 0.01) or normal pituitaries (P = 0.001)." (PMID 30867568, 2019). "In this study, we provide evidence that polyP exists in CRC and adenomas with high-grade dysplasia, expressed mainly by CD68-positive (CD68+) mast cells and located in close proximity with neutrophils." (PMID 29543850, 2018). "This is the first time that polyP was shown to be expressed by CD68+ mast cells in malignant and pre-malignant environment, namely that of colonic adenocarcinoma and adenomas with high-grade dysplasia." (PMID 29543850, 2018). "In the stroma of our adenomas, macrophages (CD68+) were slightly more numerous than CD8+ or FOXP3+ T cells, but they were far less abundant than CD4+ T cells." (PMID 27441558, 2016). "However, a study where TAMs were examined in the low-grade dysplasia (LGD)–high-grade dysplasia (HGD)–invasive carcinoma pathway has shown a rise in CD68+ cells in adenomas, which was followed by a decrease in the invasive carcinoma stage." (PMID 40149674, 2025). "Additionally, the number of CD68+ macrophages was found to be higher in sparsely granulated growth hormone (SG-GH) adenomas and null cell adenomas than in densely granulated growth hormone (DG-GH) adenomas or ACTH adenomas." (PMID 38716256, 2024). "An increased macrophage (CD68+ cells) infiltration was also observed in aryl hydrocarbon receptor interacting protein (AIP)-mutated PAs and was associated with the invasiveness of AIP-mutated adenomas." (PMID 33362722, 2020). "In conclusion, our data indicate that the exclusive presence of CD68+ polyP-expressing cells in colon adenocarcinoma and adenoma sections is a specific marker of the neoplastic colon and could possibly provide a potential prognostic marker." (PMID 29543850, 2018). "Interestingly, miR-17 was commonly altered in adenomas and associated with NOS2 in IBD while miR-181b was altered in adenomas and associated with CD68." (PMID 22970173, 2012). "IHC staining of unmatched normal colon, adenoma, and CRC patient samples for TLR4, vimentin, and CD68 was performed in a limited cohort to identify myofibroblasts and macrophages, respectively." (PMID 24887394, 2014).
adenoma (continued). "In contrast, pro-inflammatory markers (IL6, CD68, CD15, TLR4) expression is higher in adenocarcinoma tissues respect to the adenoma, the ulcerative colitis and the healthy tissues." (PMID 21059221, 2010). "It has been reported that the number of CD68+ macrophages in sparsely granulated GH-secreting adenomas is greater than in ACTH adenomas, and nonfunctional adenomas show more infiltrating CD68+ macrophages than ACTH adenomas." (PMID 36831707, 2023). "We also suggest that polyP staining, combined with immunostaining for CD68, is tumor specific and could be possibly used as a prognostic marker in CRC and adenomas." (PMID 29543850, 2018). "In all CRC and all adenomas with high-grade dysplasia, a substantial number of mast cells, more than 50%, co-expressed intracellularly polyP with CD68 surface antigen (CD68+), but this was not the case in the other examined disorders." (PMID 29543850, 2018). "As a result, the detection of CD68+ polyP-expressing cells exclusively in neoplastic conditions of colorectal tissue could be promising for assessment as a prognostic tool in CRC and adenomas." (PMID 29543850, 2018). "For null cell adenomas, a subtype of NFPA, it was observed that CD68+ macrophage infiltration was higher than that in ACTH-secreting adenomas and densely granulated GH-secreting adenomas, which indicates that null cell adenomas may have affected the statistical results of NFPAs in other studies." (PMID 34925244, 2021). "However, CD68+ polyP-expressing cells were detected only in CRC and adenomas with high-grade dysplasia, while in the adenomas with low-grade dysplasia, and in non-neoplastic cases, polyP-expressing cells were consistently CD68-negative." (PMID 29543850, 2018).